HAAO (3-hydroxyanthranilate 3,4-dioxygenase)
Diseases named in the same sentence as HAAO in open-access papers (continued):
Sharing a sentence is not in itself a finding about the gene and the disease.
tumor (9 papers, 2020 to 2025). "Taken together, these data demonstrate that HAAO is positively correlated with ferroptosis responses in tumorigenesis, implying a potential role of HAAO as a tumor suppresser via ferroptosis." (PMID 36627132, 2023). "Together, these data revealed that HAAO abrogates 3‐HK or 3‐HA mediated ferroptosis resistance to inhibit tumor cell growth via depleting cellular 3‐HA." (PMID 36627132, 2023). "In the data set for the seven matched pairs of chromophobe RCC versus normal kidney, very similar results as for ccRCC were obtained, with expression of QPRT, KMO and HAAO being below the level of detection in tumours (with one exception)." (PMID 32390008, 2020). "The effect of SAM to decrease methylation was proved to be beneficial in certain genes (HT-29: DTX1, GATA4, SEZ6L, TP53INP1; SW480: HAAO, TAL1), whose hypermethylation was associated with tumor progression according to the scientific literature." (PMID 32784836, 2020). "The results revealed that the expression of MAOA, AKR1A1, ALDH9A1, HAAO, and ALDH2 was significantly downregulated in ESCC tumor tissues compared to non-tumor tissues." (PMID 40821701, 2025). "The expression of MAOA, AKR1A1, ALDH9A1, HAAO, and ALDH2 was significantly downregulated in ESCC tumor tissues compared to non-tumor tissues." (PMID 40821701, 2025). "Similarly, HAAO and ADCYAP1, which regulate metabolic and angiogenic pathways, are frequently hypomethylated, enhancing tumor growth and immune evasion." (PMID 40528483, 2025).
cancer (8 papers, 2019 to 2025). A tumor composed of atypical neoplastic, often pleomorphic cells that invade other tissues. "Previous studies have demonstrated that the HAAO gene is associated with cancer biomarkers and degenerative diseases." (PMID 35386263, 2022). "HAAO was expressed in almost all cancer cell lines, while KYNU was detectable in CFPAC‐1 and 786‐O cells." (PMID 36627132, 2023). "As HAAO is almost detectable in a panel of cancer cell lines, we guess that degradation of 3‐HA by HAAO might confer cells sensitive to ferroptosis." (PMID 36627132, 2023). "To validate whether these enzymes regulate 3‐HA mediated ferroptosis, we first examined the expression levels of KYNU and HAAO in a panel of cancer cell lines." (PMID 36627132, 2023). "Additionally, the expression level of HAAO is positively correlated with lipid peroxidation and improved overall survival in the patients with multiple types of cancers." (PMID 36627132, 2023). "Of note, HAAO, MGLL, and UPGE were down-regulated in 18 cancer types; ADHFE1, CAT, and MSRA were down-regulated in 19; and RGN was down-regulated in 21 different types of cancer." (PMID 31351478, 2019). "When comparing RM with PC, we identified key regeneration-related genes APOD and IBSP, along with several significant pathways: cAMP signaling pathway (HHIP), cytokine-cytokine receptor interaction (IL17D), pathways in cancer (HHIP, DAPK2), and biosynthesis of cofactors (RDH12, HAAO)." (PMID 39684926, 2024).
infection (3 papers, 2016 to 2025). The state of being infected such as from the introduction of a foreign agent such as serum, vaccine, antigenic substance or organism. "Paralleling trends in the CNS of these animals, we found that upstream enzymes (IDO1, KMO, and KYNU) displayed significant mRNA upregulation during at least one phase of infection, while downstream enzymes (HAAO and QPRT) were either downregulated or unchanged." (PMID 28066416, 2016).
degenerative diseases (2 papers, 2022 to 2024). "Combined, this evidence suggests that HAAO disruption may be doubly beneficial for the treatment of neurodegenerative disease pathogenesis in both increasing 3HAA and decreasing QA." (PMID 38786006, 2024).
malformation syndrome (1 paper, 2021). "The authors described pathogenic variants in the KYNU and HAAO gene to be causative for this malformation syndrome (VCRL1, OMIM # 617660 and VCRL2, OMIM # 617661)." (PMID 34200361, 2021).
HAAO also shares sentences with these, for which no sentence is quoted: glioma (3 papers); Huntington disease (2); neurologic disorders (2); schizophrenia (2); alcoholic hepatitis (1); Anxiety (1); breast carcinoma (1); cocaine dependence (1); Hypercholesterolemia (1); insomnia (1); lung adenocarcinoma (1); lung carcinoma (1); marijuana dependence (1); neuroblastoma (1); neurodevelopmental disorder (1); non‐alcoholic steatohepatitis (1); Obesity (1); opiate dependence (1); prostate carcinoma (1); psychiatric disorder (1); rectum adenocarcinoma (1).